ELAPOR1 (endosome-lysosome associated apoptosis and autophagy regulator 1)
Description:
May protect cells from cell death by inducing cytosolic vacuolization and up-regulating the autophagy pathway. May play a role in apoptosis and cell proliferation through its interaction with HSPA5.
Synonyms: EIG121; KIAA1324; maba1
Tractability: Antibody: UniProt places it where antibodies can reach, with high confidence; its Gene Ontology location is reachable by antibodies, with high confidence; UniProt predicts a signal peptide or a membrane-spanning region; the Human Protein Atlas places it where antibodies can reach.
Gene: Protein-coding gene on chromosome 1 (109,113,175 to 109,206,781, forward strand). Ensembl gene ENSG00000116299.
Subcellular location: Cell membrane; Late endosome membrane; Golgi apparatus, trans-Golgi network membrane; Lysosome membrane; Endoplasmic reticulum membrane
Subcellular location (Human Protein Atlas): Plasma membrane
Gene Ontology:
Molecular function: RNA binding
Biological process: autophagosome assembly; cellular response to starvation; positive regulation of autophagosome assembly; positive regulation of vacuole organization
Cellular component: endoplasmic reticulum membrane; extracellular exosome; late endosome; late endosome membrane; lysosomal membrane; lysosome; plasma membrane; trans-Golgi network; Golgi apparatus
Genetic constraint (gnomAD): Loss-of-function variants: 73 observed, 115.55 expected, observed/expected ratio (o/e) 0.63, 90% interval 0.52 to 0.77. The upper end of that interval is the gene's LOEUF score, 0.77, which puts it in group 3 of 6, group 1 being the genes least tolerant of losing a copy. Missense variants: 1,088 observed, 1,287.3 expected, observed/expected ratio (o/e) 0.85, 90% interval 0.8 to 0.89. Synonymous variants: 474 observed, 495.28 expected, observed/expected ratio (o/e) 0.96, 90% interval 0.89 to 1.03.
Homologues: Orthologues: chimpanzee ELAPOR1 (99% identical), pig ELAPOR1 (93% identical), rabbit ELAPOR1 (93% identical), dog ELAPOR1 (92% identical), mouse Elapor1 (90% identical), rat Elapor1 (89% identical), guinea pig ELAPOR1 (88% identical), tropical clawed frog elapor1 (60% identical), zebrafish elapor1 (54% identical). Paralogues in human: ELAPOR2 (54% identical).
Diseases named in the same sentence as ELAPOR1 in open-access papers:
ELAPOR1 is named in the same sentence as 20 diseases in open-access papers, as found by Europe PMC text mining. Sharing a sentence is not in itself a finding about the gene and the disease. The quoted sentences say what the papers report.
gastric cancer (6 papers, 2018 to 2023). A primary or metastatic malignant neoplasm involving the stomach. "Many studies have reported KIAA1324 (also known as ELAPOR1 or inceptor) as a tumor suppressor and prognostic marker in various cancers including gastric cancer." (PMID 37612293, 2023).
muscular dystrophy (1 paper, 2022). Muscular dystrophy (MD) refers to a group of more than 30 genetic diseases characterized by progressive weakness and degeneration of the skeletal muscles that control movement. "It has also been found to exacerbate disease in a Drosophila model of muscular dystrophy, and its closest human ortholog ELAPOR1 is a regulator of apoptosis and autophagy." (PMID 35435227, 2022).
tumor (13 papers, 2013 to 2025). "Additionally, the genes in the Light-Yellow module include SPDEF, ELAPOR1, C9orf152, PLPP2, and SCGB2A1 and may be involved in several biological processes including tumor immunity and epithelial cell differentiation." (PMID 39596419, 2024).
ELAPOR1 also shares sentences with these, for which no sentence is quoted: cancer (10 papers); endometrial cancer (7); breast carcinoma (6); ovarian carcinoma (2); pancreatic carcinoma (2); adenoma (1); colon cancer (1); diabetes (1); endometrial adenocarcinoma (1); endometrioid carcinoma (1); endometriosis (1); hepatocellular carcinoma (1); Infertility (1); lung carcinoma (1); ovarian endometriosis (1); serous carcinoma (1); serous ovarian cancer (1).